UQCR11 (ubiquinol-cytochrome c reductase, complex III subunit XI)
Description:
Component of the ubiquinol-cytochrome c oxidoreductase, a multisubunit transmembrane complex that is part of the mitochondrial electron transport chain which drives oxidative phosphorylation. The respiratory chain contains 3 multisubunit complexes succinate dehydrogenase (complex II, CII), ubiquinol-cytochrome c oxidoreductase (cytochrome b-c1 complex, complex III, CIII) and cytochrome c oxidase (complex IV, CIV), that cooperate to transfer electrons derived from NADH and succinate to molecular oxygen, creating an electrochemical gradient over the inner membrane that drives transmembrane transport and the ATP synthase. The cytochrome b-c1 complex catalyzes electron transfer from ubiquinol to cytochrome c, linking this redox reaction to translocation of protons across the mitochondrial inner membrane, with protons being carried across the membrane as hydrogens on the quinol. In the process called Q cycle, 2 protons are consumed from the matrix, 4 protons are released into the intermembrane space and 2 electrons are passed to cytochrome c. QCR10 has a role in CIII assembly and RIP1 stability.
Synonyms: UQCR; QCR10; 0710008D09Rik
Tractability: Small molecule: a structure with a bound ligand is known. Antibody: UniProt predicts a signal peptide or a membrane-spanning region. PROTAC: ubiquitination databases record sites on it.
Gene: Protein-coding gene on chromosome 19 (1,597,154 to 1,605,500, reverse strand). Ensembl gene ENSG00000127540.
Subcellular location: Mitochondrion inner membrane
Pathways (Reactome):
Metabolism: Complex III assembly; Respiratory electron transport
Gene Ontology:
Molecular function: electron transfer activity
Biological process: cellular respiration; generation of precursor metabolites and energy; mitochondrial electron transport, ubiquinol to cytochrome c
Cellular component: mitochondrial inner membrane; mitochondrion; respiratory chain complex III
Genetic constraint (gnomAD): Loss-of-function variants: 10 observed, 7.44 expected, observed/expected ratio (o/e) 1.34, 90% interval 0.81 to 1.9. That is too few expected variants to judge how well the gene tolerates losing a copy. Missense variants: 86 observed, 72.59 expected, observed/expected ratio (o/e) 1.18, 90% interval 0.99 to 1.42. Synonymous variants: 34 observed, 32.45 expected, observed/expected ratio (o/e) 1.05, 90% interval 0.8 to 1.39.
Homologues: Orthologues: dog UQCR11 (86% identical), guinea pig UQCR11 (86% identical), mouse Uqcr11 (84% identical), pig UQCR11 (84% identical), rat Uqcr11 (84% identical), rat LOC120097699 (77% identical), rat Uqcr11l1 (75% identical), tropical clawed frog uqcr11 (66% identical).
Diseases named in the same sentence as UQCR11 in open-access papers:
UQCR11 is named in the same sentence as 20 diseases in open-access papers, as found by Europe PMC text mining. Sharing a sentence is not in itself a finding about the gene and the disease. The quoted sentences say what the papers report.
Alzheimer disease (3 papers, 2016 to 2022). A progressive, neurodegenerative disease characterized by loss of function and death of nerve cells in several areas of the brain leading to loss of cognitive function such as memory and language. "UQCR11 plays an important role in the conversion of mild cognitive impairment to Alzheimer’s disease and is associated with mitochondrial dysfunction." (PMID 36079709, 2022). "Genes identified by our method suggest putative roles of several biological processes in Alzheimer’s disease, including mitochondrial dysfunction (indicated by UQCR11, MTCH2 and TMEM135), cholesterol transportation (indicated by TMEM135 and OSBP), and neuron activity (indicated by ADRA1A)." (PMID 33137096, 2020).
atherosclerosis (2 papers, 2020 to 2021). A disease characterized by the build-up of fatty material and calcium deposition in the arterial wall resulting in partial or complete occlusion of the arterial lumen. "Our study identified seven core genes (UQCR11, UBE2N, ADD1, TLN1, IRAK3, LY96, and MAP3K1) that are strongly linked to FH and lead to a higher risk of atherosclerosis." (PMID 32760426, 2020). "Through analysis of the public database, seven hub genes (UQCR11, UBE2N, ADD1, TLN1, IRAK3, LY96, and MAP3K1) have recently been found to be strongly associated with familial hypercholesterolemia and contribute to a higher risk of atherosclerosis." (PMID 34895070, 2021).
breast carcinoma (1 paper, 2019). "The gene UQCR11 is differentially expressed in both lung adenocarcinoma and breast cancer, but its specific significance in tumors has not been analyzed." (PMID 31795990, 2019).
hearing loss (1 paper, 2025). "The discovery that methylation at the promoter regions of DNMT3A, UQCR11, POLQ, and SIGLEC5 has a protective effect against hearing loss suggests a multifaceted mechanism by which epigenetic regulation preserves auditory function." (PMID 40428348, 2025).
prostate carcinoma (1 paper, 2019). A carcinoma that arises from epithelial cells of the prostate gland. "As a result, the high expression of the USP34 has a protective effect on prostate cancer recurrence in TCGA and GEO gene expression profile, and the gene NDUFA13, UQCR11 is the opposite." (PMID 31795990, 2019). "We finally screened three genes related to prostate cancer recurrence: NDUFA13, UQCR11, USP34." (PMID 31795990, 2019). "So, further we expect that Low-dose lymphocyte immunotherapy might be an effective therapy for prostate cancer, and even NDUFA13, UQCR11, and USP34 might be immunocheckpoints like PD-1/ PD-L1, they may play its role through Th2 and Tcm cells." (PMID 31795990, 2019).
schizoaffective disorder (1 paper, 2019). "Genes with the least variable localization included components of the ubiquinol-cytochrome c reductase complex (Uqcrq, Uqcr11), ATP synthase complex (Atp5e, Atp5k), and ribosomal subunits (Rplp0, Rps25), some of which in humans have been implicated in schizophrenia and schizoaffective disorder." (PMID 30678683, 2019).
tumor (5 papers, 2019 to 2025). "Moreover, the high expression of the gene NDUFA13 and UQCR11 may inhibit the body’s immune system from recognizing tumors, and the probability of tumor recurrence will be significantly improved." (PMID 31795990, 2019). "Through WGCNA and Lasso, we identified that NDUFA13, UQCR11, and USP34 involved in the infiltration of Th2 cells and Tcm in tumor tissues, and the expression of genes is related to the recurrence of patients." (PMID 31795990, 2019). "Building on our network result that key gene set 2 is enriched for mitochondrial energy metabolism, the late-stage regulators we identified—UQCR11, NDUFB4, PRDX3, and S100A10—map to pathways that could support or amplify ADSCs-to-tumor bioenergetic coupling." (PMID 41325391, 2025).
cancer (3 papers, 2019 to 2023). A tumor composed of atypical neoplastic, often pleomorphic cells that invade other tissues. "Among the 102 feature genes, eight genes (MYLK, GADD45A, ACADM, UQCR11, TST, PTCD3, SOD1, CD151) were significantly enriched in the cancer hallmark of adipogenesis." (PMID 36905391, 2023). "Transcripts of UQCR11 and UQCRQ, the down-regulation of which was verified in our study via RT-qPCR, were also described to be regulated in carcinoma." (PMID 30602369, 2019).
UQCR11 also shares sentences with these, for which no sentence is quoted: Huntington disease (2 papers); Parkinson disease (2); cardiac hypertrophy (1); familial hypercholesterolemia (1); heart diseases (1); heart failure (1); lung adenocarcinoma (1); mild cognitive impairment (1); neurodevelopmental disorder (1); ovarian carcinoma (1); schizophrenia (1); Sepsis (1).